CEBPA (CCAAT enhancer binding protein alpha)
Diseases named in the same sentence as CEBPA in open-access papers (continued):
Sharing a sentence is not in itself a finding about the gene and the disease.
tumor (continued). "NPM1, RUNX1, and CEBPA are all genes from common genomic gains observed in a meta-analysis of copy number alterations across a panel of different cancer cell lines and tumor samples." (PMID 29738475, 2018). "This concept is in accordance with the experimental demonstration of anti-tumor effects of D2-HG, which decreases the stability of MYC/CEBPA transcripts via N6-methyladenosine RNA modification and thereby inhibits tumor cell survival and proliferation." (PMID 30416682, 2018). "In accordance, elevated CEBPA mRNA levels negatively affected patient survival (p<0.001) and tumor response to the PC therapy (p=0.014)." (PMID 27602952, 2016). "Strong c-Myc DNA binding activity was determined for one of the two promoter sites of the Cebpα promoter and this factor is part of the composite module that defines the up-regulated tumor specific gene expression dataset." (PMID 26427040, 2015). "Further, the genes related to AT development (PPARγ and CEBPα) were down-regulated on day 4 after tumor cell inoculation (very early stage)." (PMID 25807446, 2015). "Comparison of gene expression in Set 1 with the Sanger COSMIC dataset identified five down-regulated genes that have previously been confirmed to result in neoplasia; these included CEBPA, ERBB2, EXT1, PIM1, and SDHD." (PMID 25023465, 2014). "These are known tumor suppressor (CEBPA) and proto-oncogene (FES) that have been shown to be mutated in several tumor types." (PMID 24667986, 2014). "Mitotic index in the tumors was significantly higher in CebpαΔ/Δ mice than in control mice at 20 wk after urethane injection, suggesting that the deletion of C/EBPα enhanced tumor proliferation." (PMID 23437297, 2013). "This study reports the activation of the tumour-suppressive miR-29b by the haematopoietic key transcription factor CEBPA." (PMID 20628397, 2010). "In this study, we focused on CEBPA-regulated miRNAs with tumour-suppressive functions in haematopoiesis, and miR-29b represented the most prominent candidate." (PMID 20628397, 2010). "Additionally, we conducted an expression analysis of CEBPα and DHX58 in rat tumor models, revealing that both CEBPA and DHX58 were highly expressed in tumors, whereas their expression was markedly lower in normal gastric tissues." (PMID 41569991, 2026). "Furthermore, saRNA targeting CEBPA has shown 2.5–3-fold mRNA upregulation, growth inhibition, and reduced tumor burden." (PMID 41020855, 2025). "CRABP2, KRT14, and CEBPA expressions were significantly increased in STAS tumor cells." (PMID 40786043, 2025). "Further investigation is warranted to ascertain whether the inhibition of CEBPA and RUNX1 mutations can activate tumor immunity." (PMID 40313949, 2025). "Moreover, elevated expression of CEBPA has been demonstrated to impede tumor progression and attenuate the metastatic propensity of PDAC." (PMID 38965606, 2024). "Similarly, we extracted proteins from various tumor cell groups to analyze the expression levels of CEBPA and P21." (PMID 38965606, 2024). "Specifically, miR‐31 directly targets the tumour suppressors CCAAT enhancer binding protein α (CEBPA) and dachshund family transcription factor 1 (DACH1), which decreases β‐catenin protein level via increasing Wnt/β‐catenin signalling inhibitors, such as AXIN1, CD9 and CD82." (PMID 38797942, 2024). "Some use LNPs to deliver mRNAs that can downregulate the expression of oncogenes, such as the MYC transcription factor, or upregulate the expression of tumor suppressor genes, such as the gene encoding alpha CCAAT enhancer-binding protein (CEBPA, also known as C/EBPα)." (PMID 39065798, 2024). "Moreover, in a mouse model of PDAC, the tTR14-decorated tFNA-mediated delivery of CEBPA-saRNA effectively upregulated the expression of the CEBPA and P21 genes, consequently suppressing tumor growth." (PMID 38965606, 2024). "Therefore, miR‐31 possibly promotes PTC development through repressing tumour suppressors, especially CEBPA and DACH1." (PMID 38797942, 2024).
tumor (continued). "Mechanistic studies revealed that compound 39 could inhibit FTO activity, increase the methylation levels of c-Myc and CEBPA mRNA, and reduce the stability of their transcripts, thereby suppressing related signals and inhibiting tumor progression." (PMID 38711100, 2024). "Moreover, patients showing modifications of CEBPA, FGFR4, MET or KMT2B genes detected in circulating tumor DNA before ICI initiation are at higher risk of experiencing irAEs." (PMID 36900420, 2023). "CEBPA, a tumor suppressor, was decreased in both LM3 derivatives." (PMID 38102722, 2023). "(2016) investigated the effects of saRNA-targeting CEBPA in a mouse orthotopic HCC tumor model." (PMID 36700046, 2022). "Some alterations, such as CEBPA and CACNA1A mutations, were completely or predominantly late‐clonal and often occurred after genome duplication, suggesting that these alterations contribute to tumour maintenance and progression." (PMID 35061935, 2022). "Importantly, the expression of CEBPA in NPC patients’ tissues was significantly decreased comparing to the non-tumor nasopharyngeal tissues." (PMID 34482361, 2021). "An earlier study demonstrated that peritoneal macrophages collected from tumor-bearing mice have diminished CEBPA expression levels and have marked reduction of IL12 production upon stimulation—a phenotype that is consistent with MDSC immunosuppressive characteristics." (PMID 34770939, 2021). "Furthermore, CEBPA protein is found to be downregulated in the peritoneal macrophages of tumor-bearing mice." (PMID 34502076, 2021). "Myeloid lineage specific genetic ablation of CEBPA has been shown to promote tumor growth by increasing the number and tumor infiltration of myeloid-derived suppressor cells (MDSC) leading to a pro-angiogenic, immune suppressive and pro-tumorigenic environment." (PMID 34502076, 2021). "And thus, CEBPA is known as a putative tumor suppressor, and it is downregulated in solid tumors." (PMID 34336665, 2021). "ERBB2, CEBPA and TCF7L2 mutated tumors tend to have higher tumor mutation burden (TMB)." (PMID 34970478, 2021). "However, the opposite observations were made amongst HCC patients, where higher CEBPα mRNA was observed in tumor versus adjacent normal tissue sections." (PMID 34298689, 2021). "CEBPA acts as a tumor suppressor and was found to be down regulated in 50% of II and IIIA LUAD." (PMID 34970478, 2021). "In addition, AKT2 (p = 0.002) and KAT6A (p = 0.015) amplifications were more frequent in tumor samples from younger patients (<60), and CEBPA (p = 0.028) and MYC (p = 0.023) amplifications were more common with advanced (stage III and IV) disease stage." (PMID 32877461, 2020). "CEBPA has been proved as a tumor-inhibiting factor and is related to various types of cancers." (PMID 33150481, 2020). "In patient AML#2, both WES and targeted deep sequencing showed a homozygous non-frameshift insertion (c.937_938insCAG, p.K313delinsQK) of CEBPα, involving the bZIP domain, in the majority of tumor-cell population, as revealed by MF>80%, both at diagnosis and at relapse." (PMID 27462774, 2016). "Among them, we identified the tumour-suppressive miR-29a/b1 cluster to be a direct target of CEBPA." (PMID 20628397, 2010). "Further investigation revealed that this interesting phenomenon may be related to R-2HG, a metabolite of IDH, compound 39 (R-2HG, FTO IC50 = 133.3 μM) can affect the FTO/m6A/MYC/CEBPA pathway and inhibit tumor proliferation and survival by repressing the expression of FTO." (PMID 38711100, 2024). "CREBBP, CEBPA, and DNMT3A are tumor suppressor genes whose dysfunction has been reported in hematologic malignancies." (PMID 40216811, 2025).
tumor (continued). "CEBPA participates in chemoresistance through METTL3/METTL14/BHLHB9 in vivo, which accelerated the tumor growth." (PMID 40297811, 2025). "FTO exerts oncogenic effects on various types of cancer cells, promoting tumor cell growth by activating survival and cell-cycle signaling, such as PI3K/Akt/mTOR pathway, MYC, β-catenin, and CEBPA." (PMID 40234389, 2025). "Decreasing in proliferation, invasion, migration, and EMT of MDA-MB-231 and A375 cancer cells in vitro and BC tumor size in vivo.↓ mRNA stability of PPARG, CEBPA, and CEBPB.↑ mRNA stability of SOCS1.↑ drug sensitivity." (PMID 41157107, 2025). "While there is no recurrent gene amplification that was observed, the following genes were amplified in two tumor samples: MET, SMO, ERBB2, BRAF, EZH2, SRSF2, CUX1, and CEBPA." (PMID 38164123, 2024). "Notably, saRNAs designed to target CEBPA have previously exhibited the capability to augment the expression of CEBPA along with its downstream effector, cyclin-dependent kinase inhibitor 1 (P21), inducing an antitumor response and diminishing tumor volume in murine PDAC models." (PMID 38965606, 2024). "MiR‐31 represses tumour suppressors DACH1 and CEBPA, which otherwise direct the CD9, CD82 and AXIN1 expression." (PMID 38797942, 2024). "To identify novel tumor suppressive epigenetic regulators in AML, we performed an in vivo short hairpin RNA (shRNA) screen in the context of CEBPA mutant AML." (PMID 36631623, 2023). "The tumor suppressors ETV6, CEBPA, IRF8, and IRF1 are among the lineage-controlling master TFs found in CD141-positive monocytes enriched with SE-associated genes upregulated by cortistatin A." (PMID 37501079, 2023). "A parallel analysis was performed in ESCC, which identified a number of tumor-specific factors, including RUNX1/3, SOX2/4, and CEBPA/B." (PMID 37620896, 2023). "Aiming to identify novel epigenetic regulators in AML, we performed an shRNA-screen using a murine model of CEBPA mutant AML and identified KDM5C as a novel tumor suppressor." (PMID 36631623, 2023). "KDM6B knockdown can inhibit the expression of the CCAAT-enhancer binding protein alpha (CEBPA) gene and enhance tumor progression of PC cells both in vitro and in vivo." (PMID 35296007, 2022). "TCGA data analysis and IHC staining of clinical tumor samples showed that ASNS and CEBPA tended to be underexpressed in the Cluster 2 with poor prognosis." (PMID 35174151, 2022). "The results showed that the relative expression of CXCL12, CEBPA, and TUBA1A in tumor cells was significantly lower than that in normal cells (all P < 0.05)." (PMID 34225733, 2021). "Treatment with demethylating agents restores CEBPA expression in DLPS, is antiproliferative and proapoptotic in vitro and reduces tumor growth in vivo." (PMID 28654693, 2017). "Analysis of more tumor samples will be needed to definitively establish/verify a relationship between natural platinum resistance and TRIB2 and CEBPA protein expression." (PMID 29312632, 2017). "Similar patterns were also observed in limited human tumor specimens of chemo-resistant SCLC patients: namely, overexpressed TRIB2 and undetected CEBPA proteins." (PMID 29312632, 2017). "Despite a subtle increase in expression in the tumor tissue and positive variation for some of the animals in liver, mRNA levels for CEBPA do not change significantly with the treatment, in any of the tissues." (PMID 40226120, 2025). "Likewise, we detected reduced CEBPA and DACH1 staining in miR‐31‐overexpressing tumours, whereas increased CEBPA and DACH1 in mPTC/miR‐31−/− tumours." (PMID 38797942, 2024). "Although beyond the scope of this work, it is tempting to speculate that FOSL1-mediated CEBPA depletion and reduced CEBPA-FOS/JUN interaction work in concert to promote tumor aggressiveness." (PMID 36631623, 2023). "We next determined the expression levels of CEBPA in tumor xenografts with or without LMP1 expression." (PMID 34482361, 2021).
tumor (continued). "Mice with knock-out of CEBPA have an increase in the number of myeloid-derived suppressor cells (MDSC) in the tumor, increased expression of proangiogenic markers and accelerated tumor growth." (PMID 34770939, 2021). "We performed whole-exome sequencing (WES) of tumor-normal matched samples of de novo AML-NK patients lacking mutations in NPM1, CEBPA or FLT3-ITD to identify new gene mutations with potential prognostic and therapeutic relevance to patients with AML." (PMID 30303964, 2018). "Other known tumor suppressors such as WT1, CEBPA or CDKN1A are instead missed by our analysis." (PMID 26860319, 2016). "CEBPA, CCAAT/enhancer-binding protein alpha, is a tumor-suppressor gene." (PMID 24667986, 2014). "Late-deletion of C/EBPα significantly increased the number and size of lung tumors and the tumor burden in on-Dox CebpαΔ/Δ mice compared to no-Dox Cebpaflox/flox mice." (PMID 23437297, 2013). "However, both tumor DNA sequencing analyses (Archer VARIANTPlex Core Myeloid amplification followed by Illumina sequencing, mean CEBPA coverage 2080x and 3560x) detected no second variant in the CEBPA gene, and could not support our hypothesis for solid tumorigenesis in the proband." (PMID 40313597, 2025). "Based on the suppressive function of MDSCs in tumor-bearing mice, △9-tetrahydrocannabinol (THC)-induced MDSCs were used to confirm that miR-690 had great potential on maintaining the immunosuppression of MDSCs via decreasing the expression of CEBPα and decaying their terminal differentiation." (PMID 35634311, 2022). "It is plausible that AKT2 rather than CCNE1 or CEBPA in this dataset is the driver of the tumor." (PMID 32877461, 2020). "The literature does not provide an explicit answer, whether CEBPA is an oncogene or a tumor suppressor." (PMID 27602952, 2016). "Then, UBC could modulate STAT5A and CEBPA in the WNT and the MAPK signaling pathways to inhibit DNA repair through the dysregulation of HIST2H2BE and to induce the accumulation of autoimmune defects through the dysregulation of IGF2, which might ultimately facilitate tumor growth." (PMID 30344796, 2018). "The expression of ASNS and CEBPA in tumor tissues of Group 1 was higher than that in non-tumor normal tissues, while the expression of ASNS and CEBPA in tumor tissues of Group 2 was lower than that in non-tumor normal tissues." (PMID 35174151, 2022).
cancer (156 papers, 2006 to 2026). A tumor composed of atypical neoplastic, often pleomorphic cells that invade other tissues. "CEBPA, which is associated with the controlling of neutrophil development, was significantly upregulated in advanced cancer." (PMID 38719807, 2024). "Cancer mutations of the bZip domain of CEBPA disrupt not only the DNA binding function, but the dimerization domain as well." (PMID 33806614, 2021). "In fact, some genes, such as HRAS, YOD1, VHL, and CEBPA, were among the most important genes for several cancer types even though their number of mutations in TCGA is very small compared to other genes (ranging from the 4th to 16th percentile)." (PMID 34385450, 2021). "Recent studies have shown that HCC is caused by the de-differentiation of hepatocytes into cancer stem cells; the dephosphorylation of the tumor suppressor CEBPα at Ser193 or the mutation of Ser193 to Ala results in this process." (PMID 34298689, 2021). "The CEBPA gene is known to be mutated or abnormally expressed in several cancers." (PMID 27602952, 2016). "CCAAT/enhancer binding protein α (CEBPA), as a versatile ligand-independent transcriptional factor, has an important function in myeloid cells, and is under clinical evaluation for cancer therapy." (PMID 38557493, 2024). "Genes of particular interest within the set of 57 included two genes with well-established cancer associations by COSMIC25: alpha-thalassemia mental retardation X-linked (ATRX) and CCAAT enhancer binding protein alpha (CEBPA)." (PMID 38442712, 2024). "depicted for the first time, that CEBPA is involved in chemotherapeutic resistance and cancer stemness by affecting the MAPK14/C/EBPα signaling pathway in BC." (PMID 37483521, 2023). "Dysregulation of CEBPA expression is widely reported in human cancer, for which various mechanisms have been described." (PMID 37857015, 2023). "The expression of CEBPA was decreased in cancer samples in GSE54129 dataset and formed DRLs with CLCA1, CES2." (PMID 35421923, 2022). "The regulation of CEBPA accelerated cancer progression by disrupting circadian rhythm-signaling pathway." (PMID 35698045, 2022). "The combination of CEBPB siRNA with CEBPA saRNA in transfection experiments resulted in a more pronounced reduction in the proliferation of cancer cell lines." (PMID 34770939, 2021). "Beyond N-terminal CEBPA mutations in AML, other scenarios exist where a truncated transcription factor isoform retains the capacity of actively changing gene expression in cancer." (PMID 31867767, 2020). "It was also reported that some drugs with antitumor activity, such as R-2-hydroxyglutarate (R-2HG), inhibited proliferation/survival of FTO-high cancer cells via targeting FTO/m6A/MYC/CEBPA signaling." (PMID 32754191, 2020). "The dedifferentiation of cancer cell was inhibited through inhibition of IL-6, CCAAT/enhancer binding protein alpha (CEBPα), Spi-1 proto-oncogene (PU.1), c-Myc and E2F transcription factor 1 (E2F1)." (PMID 30373594, 2018). "After multivariate cox’s model filtering, we identified 4 mRNAs (MLLT3, CEBPA, HIST2H3C and AFF1) in ‘Transcriptional misregulation in cancer’ pathway were independently associated with prognosis." (PMID 30181715, 2018). "The deletion of C/EBPα in CebpαΔ/Δ mice strikingly increased the urethane-induced lung tumor incidence and the malignant tumors." (PMID 23437297, 2013).